RNU6-1265P (RNA, U6 small nuclear 1265, pseudogene)
Gene: Small nuclear RNA gene on chromosome 1 (14,124,233 to 14,124,335, reverse strand). Ensembl gene ENSG00000252151.
Homologues: Orthologues: chimpanzee U6 (97% identical), macaque U6 (90% identical), mouse Gm22549 (81% identical). Paralogues in human: RNU6-12P (81% identical), RNU6-13P (81% identical), RNU6-32P (81% identical), RNU6-7 (81% identical), RNU6-8 (81% identical), RNU6-1 (80% identical), RNU6-1181P (80% identical), RNU6-17P (80% identical), RNU6-18P (80% identical), RNU6-19P (80% identical), RNU6-2 (80% identical), RNU6-3P (80% identical), and 1284 more.